SMAD7 (SMAD family member 7)
Diseases named in the same sentence as SMAD7 in open-access papers (continued):
Sharing a sentence is not in itself a finding about the gene and the disease.
renal fibrosis (continued). "BHD could attenuate renal fibrosis and inflammation in STZ-induced diabetic kidneys via inhibiting TGF-β1/Smad3 and NF-κB signaling while suppressing the Arkadia and restoring renal Smad7." (PMID 34775979, 2021). "Since Smad7 functions as an integrated inhibitor for both TGF-β/Smad–signaling and NF-κB–signaling pathways, once renal Smad7 is degraded, TGF-β/Smad and NF-κB signaling becomes activated, resulting in the development of renal fibrosis and inflammation." (PMID 34831368, 2021). "Overexpression of miRNA-21 promotes renal fibrosis by targeting PTEN and Smad7." (PMID 32258028, 2020). "Based on these findings, it is not surprising that overexpression of Smad7 significantly mitigated renal fibrosis in a rat unilateral ureteral obstruction model." (PMID 32215042, 2020). "Thus, knockdown of miR-21 restores renal Smad7 levels and blocks both TGF-β/Smad3 and NF-κB signaling, thereby inhibiting progressive renal fibrosis and inflammation in mouse models of obstructive and diabetic nephropathy." (PMID 32258028, 2020). "However, in the present study, we found that Smad7 protein levels in the UUO‐kidney of Gadd45β KO mice were up‐regulated, which subsequently reduce the phosphorylation of Smad2, resulting in less renal fibrosis." (PMID 32570293, 2020). "On the other hand, it also has been shown that EZH2 mediates the development of renal fibrosis by down-regulating the expression of Smad7, a negative regulator of the TGF-β signaling pathway." (PMID 30539787, 2019). "The authors suggested that SMURF2-mediated ubiquitylation/degradation of SMAD7, SnoN, and Ski might potentiate TGF-β signaling, leading to renal fibrosis." (PMID 30696809, 2019). "We also identify that prevention of Smurf2-mediated Smad7 ubiquitin degradation, thereby inhibiting both TGF-β/Smad3-mediated renal fibrosis and NF-κB-dependent renal inflammation may be mechanisms associated with the beneficial effect of TSF on DN." (PMID 26807792, 2016). "We have previously shown that Smad7 is an integrated regulator that negatively regulates TGF-β/Smad-mediated renal fibrosis via its negative feedback-loop and NF-κB-dependent renal inflammation by inducing IκBα, an inhibitor of NF-κB." (PMID 26807792, 2016). "Smad7 is a negative regulator of TGF-β1/Smad3 signaling, which may reflect its protective role in renal fibrosis." (PMID 27610006, 2016). "First, consistent with a negative regulator of Smad7 in TGF-β/Smad signaling, Smad7 may act by inhibiting the activation of TGF-β/Smad signaling, thereby blocking renal fibrosis, a major pathological feature of chronic AAN." (PMID 25883225, 2015). "Whereas, deletion of Smad7 may result in a further increase in Sp1-Smad3 interaction, thereby enhancing ANG II-mediated renal fibrosis." (PMID 23301086, 2013). "SETD2 deficiency resulted in severe renal fibrosis in the absence of VHL, and based on these results, we found that SETD2 deletion can lead to reduced expression of Smad7 by H3K36me3, which activates the TGF‐β/Smad signalling pathway and leads to renal fibrosis." (PMID 37933774, 2023). "In addition, we further confirmed that SETD2 overexpression could facilitate Smad7 transcription to inhibit the TGF‐β/Smad signalling pathway and renal fibrosis." (PMID 37933774, 2023). "Regarding the mechanism of RRR against renal fibrosis, some studies have shown that its nephroprotective effect was to reduce the expressions of TGF-β1, TGF-β receptor I (TGF-β RI), TGF-β RII, Smad2, p-Smad2, Smad3, p-Smad3, and Smad4, meanwhile increasing Smad7 (Zhang ZH." (PMID 35924053, 2022). "We found rhubarb extracts suppressed TGF-β/Smad3-mediated renal fibrosis by reducing the TGF-β1, transforming growth factor-β receptor I (TGF-β RI), transforming growth factor-β receptor II (TGF-β RII), Smad2, p-Smad2, Smad3, p-Smad3, and Smad4, meanwhile increased Smad7." (PMID 30271345, 2018).
renal fibrosis (continued). "Based on these observations, we therefore hypothesized that the combination of AA and NG may produce a better therapeutic effect on renal fibrosis by more effectively correcting the imbalance of TGF-β/Smad signaling, namely upregulation of Smad7 while suppressing Smad3." (PMID 26474462, 2015). "In the present study, we also found that addition of AA was capable of blocking Smad3 phosphorylation and renal fibrosis by upregulating Smad7 without altering expression of Smad3, identifying AA as a Smad7 agonist to inhibit Smad3 signaling by inducing Smad7 transcription." (PMID 26474462, 2015). "To investigate the mechanisms by which deletion of Smad7 promoted renal fibrosis and inflammation in mice with chronic AAN, we examined TGF-β/Smad and NF-κB signaling pathways since both pathways are critical in the development of renal fibrosis and inflammation in many pathological conditions." (PMID 25883225, 2015). "lncRNA Erbb4-IR is induced by TGF-β1 through a Smad3-dependent mechanism and binds to the 3ʹ-UTR of Smad7 to inhibit the negative effect of Smad7 on TGF-β/Smad pathway, thus promoting the development of renal fibrosis." (PMID 40083322, 2025). "Deletion of SETD2 leads to reduced Smad7 expression, which results in activation of the TGF‐β/Smad signalling pathway and ultimately renal fibrosis in the absence of VHL." (PMID 37933774, 2023). "Smad7, another downstream negative modulator of TGF-β1, was shown to be downregulated during renal fibrosis." (PMID 38255158, 2023). "CTGF is the downstream regulatory factor of TGF-β1, which inhibits the transcription of Smad7, blocks the negative feedback effect on TGF-β1, and promotes the role of TGF-β1 in the process of renal fibrosis." (PMID 30713574, 2019). "Similarly to Smad2, also Smad7, a member of inhibitory group of I-Smads, is a negative regulator of TGF-β1/Smad3 signaling, and a growing number of papers indicate its protective role in renal fibrosis." (PMID 27610006, 2016). "In addition, unlike active TGF-β1 which mediates progressive renal fibrosis, mice overexpressing latent TGF-β1 are protected against progressive renal inflammation and fibrosis in obstructive and immunologically-induced crescentic glomerulonephritis via the Smad7-dependent mechanism." (PMID 23301086, 2013).
liver fibrosis (104 papers, 2009 to 2026). "It was reported that miRNA-96 regulated schistosoma-associated liver fibrosis by targeting Smad7, an important inhibitor of TGF-β1 signaling." (PMID 39363237, 2024). "We demonstrated that PROM1 plays a central role in TGFβ signaling and liver fibrosis by stabilizing SMAD7 using both global and liver-specific Prom1-deficient mice." (PMID 36038590, 2022). "We also demonstrated that hepatocyte-specific overexpression of SMAD7 ameliorated BDL-induced liver fibrosis in liver-specific Prom1-deficient mice." (PMID 36038590, 2022). "We also demonstrate that PROM1 deficiency aggravated BDL-induced liver fibrosis and enhanced TGFβ signaling by reducing SMAD7 protein expression in hepatocytes." (PMID 36038590, 2022). "The inhibitory effect of AA in TGF-beta/Smad-mediated hepatic fibrosis was associated with upregulation of Smad7 as demonstrated by the findings that AA alone was able to induce Smad7 mRNA and protein in a time and dosage-dependent manner." (PMID 22363627, 2012). "Additionally, CHE interfered with the expression of TGF-β1, Smad4, and Smad7 proteins, further confirming its inhibitory effect on hepatic fibrosis in mice, associated with the TGF-β/Smads signaling pathway." (PMID 39239653, 2024). "Because hepatocyte-specific SMAD7 overexpression ameliorated BDL-induced liver fibrosis in liver-specific Prom1 deficiency, hepatocellular TGFβ signaling might be required for the development of liver fibrosis." (PMID 36038590, 2022). "Our previous studies showed that Smad7 was abnormally expressed in the liver of mice infected with C. sinensis, and we found that many miRNAs were involved in regulating the progression of liver fibrosis caused by C. sinensis at the post-transcriptional level." (PMID 34521449, 2021). "Collectively, miR-21 and miR-96 could promote schistosomiasis-associated liver fibrosis by targeting SMAD7 to activate the SMAD signaling pathway and increase collagen expression." (PMID 31888743, 2019). "Our results established a recent approach associating the anti-fibrotic mechanism of the non-selective β-blocker Carvedilol with the circulating miR-200a, the newly diagnostic non-invasive biomarkers of liver fibrosis, SMAD7, and through the suppression of EMT." (PMID 30254303, 2018). "In the present study, CCl4-induced liver fibrosis was associated with a marked activation of Smad2/3 but a loss of Smad7, suggesting that the imbalance between Smad2/3 and Smad7 signaling could be important in the pathogenesis of liver fibrosis." (PMID 22363627, 2012). "Praziquantel dramatically raised the expression of Smad7 in the HSCs of mice with liver fibrosis while decreasing the synthesis of collagen." (PMID 40244247, 2025). "SMAD7 inhibits the activation of HSCs, and the upregulation of SMAD7 expression suppresses the progression of liver fibrosis and HCC." (PMID 40651612, 2025). "CGA attenuates Schistosoma japonicum cercaria-induced hepatic fibrosis in animals, partially through regulating IL-13/miR-21/Smad7." (PMID 38612964, 2024). "It has been reported that schistosome infection significantly upregulated miRNA-96 expression, which elicits hepatic fibrosis by targeting SMAD7." (PMID 39363237, 2024). "Elevated Malat1 expression in infected HSCs reduces fibrosis by downregulating miR-96 and upregulating Smad7, thus providing a novel therapeutic target for schistosomiasis hepatic fibrosis." (PMID 39363237, 2024). "For example, parasite infection-mediated upregulation of both miRNA-21 and miRNA-96 induces hepatic fibrosis by targeting SMAD7, thereby relieving the inhibitory effects of SMAD7 on the TGF-β/SMAD pathway." (PMID 39363237, 2024). "In this study, FMGs inhibited TGF-β1 and Smad4 expression while increasing Smad7 expression in the injured rat liver, demonstrating their efficacy in treating liver fibrosis." (PMID 39195542, 2024).
liver fibrosis (continued). "CGA suppresses CCl4-induced liver fibrosis by suppressing miR-21/TGF-β1/Smad7 signaling or inhibiting TLR4/NF-κB signaling and stimulating the Nrf2 pathway." (PMID 38612964, 2024). "Our previous studies have shown that S. japonicum infection significantly elevates miR-21 and miR-96, which promote hepatic fibrosis by targeting Smad7." (PMID 39363237, 2024). "Further mechanisms suggest that IL-13 affects miR-21/Smad7 signaling, which in turn affects liver fibrosis." (PMID 38770001, 2024). "SMAD2, SMAD3, SMAD4, and SMAD7 expression levels were measured to determine TGF-β1 related hepatic fibrosis." (PMID 39055873, 2024). "In summary, we demonstrated that oxoglaucine significantly suppresses TGFβ-induced hepatic fibrosis, and that regulation of Smad7 levels is an important factor in the inhibition of Smad2 phosphorylation." (PMID 37446633, 2023). "CGA upregulates Smad7 expression, downregulates p-Smad2, p-Smad3, and p-Smad2/3 levels in vitro and in vivo, and has been shown to inhibit CCl4-induced liver fibrosis in Sprague-Dawley rats." (PMID 38202710, 2023). "Smad7 acts as an inhibitor, which is also a target of miR21, prevents liver fibrosis by inhibiting Smad2/3." (PMID 38202710, 2023). "Increasing evidence has demonstrated that the disruption of Smad7 expression participates in a number of diseases, including inflammatory bowel disease, hepatic fibrosis, cardiac remodeling, cancer and kidney disease." (PMID 37507781, 2023). "Based on all these data, we concluded that hepatocyte-specific PROM1 plays a central role in the regulation of TGFβ signaling and liver fibrosis via SMAD7 stabilization." (PMID 36038590, 2022). "Evidences have shown that TGF-β1/Smad2/3 signaling play a pro-fibrotic role, while IFN-γ/STAT1/Smad7 signaling pathway exhibit an anti-fibrotic role in liver fibrosis progression." (PMID 35387552, 2022). "In conclusion, ADSCs transplantation alleviated liver fibrosis in E. multilocularis infected mice by up-regulating Smad7 and down-regulating the expressions of TGF-β receptors, the activation of HSCs, and collagen deposition." (PMID 35100287, 2022). "MiRNA-21 inhibits Smad7 expression to promote TGF-β/Smad signaling-mediated liver fibrosis, and chlorogenic acid inhibits miRNA-21 expression to suppress SSLF." (PMID 36389166, 2022). "Our results suggest that hepatocyte-specific Prom1 is necessary to attenuate TGFβ-induced liver fibrosis by stabilizing SMAD7 and reducing TGFβ-induced apoptosis in hepatocytes." (PMID 36038590, 2022). "ADSCs can alleviate Echinococcus multilocularis infection-induced liver fibrosis by modulating the activity level of the TGF-β/Smad7 signaling pathway and provide a potential therapeutic approach for E. multilocularis-induced fibrosis." (PMID 35100287, 2022). "A later study on AE transplant treatment showed that through modulating the activity level of the TGF-β/Smad7 signaling pathway, liver fibrosis induced by E. multilocularis infection can be alleviated." (PMID 36439797, 2022). "Because PROM1 interfered with the molecular association of SMAD7 with SMURF2 and prevented SMURF2-induced SMAD7 ubiquitination and degradation, we conclude that PROM1 is necessary for the prevention of liver fibrosis by negatively regulating TGFβ signaling." (PMID 36038590, 2022). "H&E and Sirius Red staining revealed that SMAD7 overexpression alleviated BDL-induced liver fibrosis in Prom1f/f; Alb-Cre mice." (PMID 36038590, 2022). "The mice with liver fibrosis exhibited a significantly suppressed expression of smad-7 in the liver by 57.0% compared to the control group." (PMID 34778375, 2021). "In our present study, we found that miR-497 facilitated the TGF-β/Smad signaling pathway by targeting Smad7, which promoted the activation of HSCs and exacerbated liver fibrosis in vivo and in vitro, respectively." (PMID 34521449, 2021).
liver fibrosis (continued). "In this regard, a previous study showed that DNMT1 mediates repression of Smad7 and subsequent hepatic stellate cell activation and liver fibrosis." (PMID 33456568, 2021). "Corilagin, a plant-derived ellagitannin, was found to modulate fibrosis through the miR-21/Smad7/ERK signaling pathway in a mouse model of hepatic fibrosis." (PMID 33981353, 2021). "The expression levels of TGF-β1 and Smad3 were decreased in a carbon tetrachloride-induced liver fibrosis model in rats treated with the herbal decoction JinSanE, and Smad7 expression was found to increase." (PMID 33981353, 2021). "Our results unveil the approach of CKI in rebalancing TGF‐β/Smad7 signaling in HSCs to protect against hepatic fibrosis and hepatocarcinogenesis in both preclinical and clinical studies." (PMID 34323416, 2021). "Our results demonstrated that SSTF alleviated schistosomiasis japonica-induced hepatic fibrosis by inhibiting the TGF-β1/Smad7 pathway." (PMID 33293986, 2020). "Patients with chronic hepatitis including Schistosoma japonicum-related hepatic fibrosis exhibit downregulation of SMAD7, a negative regulator of transforming growth factor (TGF)-β signaling, which modulates fibrosis and TGF-β, in turn, induces miR-21." (PMID 33171811, 2020). "The findings suggest that the MSC therapy with Smad7-MSCs is effective in the treatment of liver fibrosis in the CCl4-induced liver cirrhosis model." (PMID 32928296, 2020). "SMAD7, a SMAD-signaling regulator, is a common target of miR-21 and miR-96 in schistosomiasis-associated hepatic fibrosis." (PMID 31888743, 2019). "5-Azacytidine, a DNMT inhibitor, restored Aggf1 expression, which led to improvement of liver fibrosis in a SMAD7-dependent mechanism." (PMID 31718044, 2019). "In model of acute liver injury, the up-regulation of Smad7 can be used as an inhibitory factor to prevent the early response of liver fibrosis and maintain a balance state in liver transducted by TGF-β1/Smad signal." (PMID 31221141, 2019). "In a recent mechanistic study, the authors showed that PZQ inhibits CCl4-induced liver fibrosis by upregulating SMAD7 in HSC." (PMID 31718044, 2019). "Knockdown of Smad7 in hepatocytes has been shown to promote liver fibrosis, but little is known about the effects of Smad7 in myeloid cells during inflammatory responses in the liver." (PMID 31698731, 2019). "In conclusion, circMTO1 suppresses the progression of liver fibrosis via regulation of miR‐17‐5p and Smad7." (PMID 31148365, 2019). "In hepatic tissues, miR-17 promoted the proliferation of hepatic stellate cells, leading to hepatic fibrosis by inhibiting Smad7." (PMID 30648109, 2018). "Accordingly, Smurf2 interacts with Smad7 to suppress TGFβ-mediated fibrosis, including liver fibrosis and tubulointerstitial fibrosis." (PMID 30450046, 2018). "This study explored the effects of CGA on miR-21-regulated TGF-β1/Smad7 liver fibrosis in the hepatic stellate LX2 cell line and in CCl4-induced liver fibrosis in Sprague-Dawley rats." (PMID 29311932, 2017). "In TGF-β/Smad signaling pathway, TGF-β plays a pro-fibrotic role, however, Smad7 plays an anti-fibrotic role and alleviates the extent of hepatic fibrosis." (PMID 28680559, 2017). "We have determined that CGA has an anti-liver fibrosis effect on schistosome-infected mice by suppressing the IL-13/miR-21/Smad7 signaling interactions and has an anti-inflammatory effect through the suppression of the TLR2/TLR9-Myd88 signaling pathways." (PMID 29311932, 2017). "miR-16 suppresses the expressions of hepatocyte growth factor (HGF) and Smad7 in HCV-induced hepatic fibrosis." (PMID 28680559, 2017). "BAMBI and Smad7 play important roles in TGF-β signal transduction in the context of the pathological development of liver fibrosis." (PMID 27594891, 2016). "Recently, a number of studies have demonstrated that co-expression of Smad7 and uPA attenuates CCl4-induced liver fibrosis in rats." (PMID 25435153, 2015).